EFEMP2 (EGF-like fibulin extracellular matrix protein 2)
Diseases named in the same sentence as EFEMP2 in open-access papers (continued):
Sharing a sentence is not in itself a finding about the gene and the disease.
ovarian carcinoma (6 papers, 2015 to 2025). A malignant neoplasm originating from the surface ovarian epithelium. "Similar to EFEMP2, PD-L1 was also highly expressed in aggressive cells and had the ability to promote the invasion and metastasis of ovarian cancer cells both in vitro and in vivo, and PD-L1 upregulation was partly caused by EFEMP2 activation." (PMID 37420173, 2023). "We have previously reported that EFEMP2 was highly expressed in ovarian cancer and was strongly associated with poor prognosis in patients." (PMID 37420173, 2023). "Our team previously demonstrated that EFEMP2 was associated with tumor progression of ovarian cancer and poor prognosis." (PMID 37420173, 2023). "Although this further verified the associated relationship between EFEMP2 expression and ovarian cancer, the current mechanism by which EFEMP2 affects ovarian tumors warrants further research." (PMID 37420173, 2023). "Moreover, EFEMP2 could bind to EGFR to induce PD-L1 regulation in ovarian cancer, which was caused by the activation of EGFR/ERK1/2/c-Jun signaling." (PMID 37420173, 2023). "Based on the phosphorylation pathway profiling array, EGFR and c-Jun were both lowly expressed after EFEMP2 was knocked down in ovarian cancer cells." (PMID 37420173, 2023). "In the same way, when EFEMP2 was knock-down, the migration and invasion abilities were also reduced, whereas the results were opposite in ovarian cancer cells overexpressing EFEMP2." (PMID 37420173, 2023). "The effects of the down-regulation and up-regulation of EFEMP2 on the biological behavior of ovarian cancer cells were studied through in-vitro and in-vivo functional tests." (PMID 37420173, 2023). "In PD-L1 knockout ovarian cancer cells, overexpression of EFEMP2 cannot promote EMT and cancer cell invasion and metastasis." (PMID 37420173, 2023). "Here, in ovarian cancer, our experiments strongly supported the notion that the oncogene EFEMP2 regulated the expression of PD-L1 driven by EGFR." (PMID 37420173, 2023). "In conclusion, EFEMP2 promoted the invasion and dissemination of ovarian cancer cells in vivo, and PD-L1 was essential in this process." (PMID 37420173, 2023). "Our subsequent studies at least partially revealed the mechanism of EFEMP2 in the invasion and metastasis of ovarian cancer." (PMID 37420173, 2023). "In one word, PD-L1 was crucial for EFEMP2 to promote ovarian cancer cells invasion and migration in vitro and in vivo." (PMID 37420173, 2023). "Although we previously found that EFEMP2 was overexpressed in ovarian cancer and related to its poor prognosis, the molecular mechanism of EFEMP2 in the metastasis and invasion of ovarian cancer cells remains elusive and needs to be further explored." (PMID 37420173, 2023). "Based on the characteristics of EFEMP2 in our research on ovarian cancer, we believed that EFEMP2 might be used as a targeted drug to effectively inhibit the invasion and metastasis of ovarian cancer in the future." (PMID 37420173, 2023). "EFEMP2 was positively related to the migration and invasion ability of ovarian cancer cells." (PMID 37420173, 2023). "Targeted therapy against the source gene EFEMP2 is our future research direction, which may better inhibit the invasion and metastasis of ovarian cancer cells." (PMID 37420173, 2023). "The decreased expression of PD-L1 could block the promotion effect of EFEMP2 overexpression on the invasion and migration of ovarian cancer cells, as well as the induction effect on EMT process." (PMID 37420173, 2023). "PD-L1 was essential for EFEMP2 to promote the invasion and metastasis of ovarian cancer cells." (PMID 37420173, 2023). "This study for the first time clarified how EFEMP2 regulated PD-L1, and in the microenvironment of ovarian cancer, EFEMP2 could target PD-L1 to promote EMT process and cancer cell invasion and metastasis." (PMID 37420173, 2023).
ovarian carcinoma (continued). "We proved for the first time that EFEMP2 could bind to EGFR to activate ERK1/2/c-Jun pathway and regulate PD-L1 expression, furthermore, PD-L1 was extremely important for EFEMP2 to promote ovarian cancer cells invasion in vitro and in vivo." (PMID 37420173, 2023). "Afatinib combined with trametinib had an obvious effect of inhibiting the intraperitoneal diffusion of ovarian cancer cells, especially in the group with low expression of EFEMP2, while overexpression of PD-L1 could reverse this phenomenon." (PMID 37420173, 2023). "The results showed that EFEMP2 down-expression could significantly inhibit the spread of ovarian cancer cells in the abdominal cavity of nude mice, but the overexpression of PD-L1 drastically promoted the process." (PMID 37420173, 2023). "Taken together, reducing EFEMP2 expression could inhibit the migration, invasion and clonogenicity of ovarian cancer cells, whereas increasing EFEMP2 expression could promote the migration, invasion and clonogenicity of ovarian cancer cells." (PMID 37420173, 2023). "Further experiments were conducted to verify whether PD-L1 played a decisive role in the EFEMP2-induced enhancement in the proliferation and invasion of ovarian cancer cells." (PMID 37420173, 2023). "We established ovarian cancer cell models with down-expression and up-expression of EFEMP2, respectively, and observed that overexpression of EFEMP2 increased the invasion ability of ovarian cancer cells, while its down-expression inhibited the invasion characteristics of ovarian cancer cells." (PMID 37420173, 2023). "Similarly, by co-transfecting EFEMP2 shRNA and PD-L1 cDNA into ES-2 cells, we investigated whether overexpression of PD-L1 could reverse the blocking effect of EFEMP2 knockout on the proliferation and invasion of ovarian cancer cells." (PMID 37420173, 2023). "RT-qPCR was used to detect the mRNA expression of EFEMP2 while western blot and ICC were performed to examine EFEMP2 protein expression in ovarian cancer cell lines." (PMID 37420173, 2023). "Therefore, high EFEMP2 expression could promote ovarian cancer cell proliferation in vivo." (PMID 37420173, 2023). "Therefore, we believed that EFEMP2 could promote the EMT process of ovarian cancer cells." (PMID 37420173, 2023). "The expression of EFEMP2 was detected by RT-qPCR, ICC and western blot in 4 kinds of ovarian cancer cells with different migration and invasion ability." (PMID 37420173, 2023). "Meanwhile, in ovarian cancer cells overexpressing PD-L1, EFEMP2 knockdown did not prevent EMT and cancer cell invasion and metastasis." (PMID 37420173, 2023). "EFEMP2 could bind to EGFR to activate ERK1/2/c-Jun pathway and regulate PD-L1 expression, furthermore PD-L1 was extremely essential for EFEMP2 to promote ovarian cancer cells invasion and dissemination in vitro and in vivo." (PMID 37420173, 2023). "In our study, both EFEMP2 and PD-L1 could promote the EMT process and increase the invasion ability of ovarian cancer cells." (PMID 37420173, 2023). "EFEMP2 cDNA and PD-L1 shRNA were co-transfected into OVCAR-3 cells to observe whether PD-L1 silencing would block the promotion effect of EFEMP2 overexpression on the proliferation and invasion of ovarian cancer cells." (PMID 37420173, 2023). "Consistent with EFEMP2, PD-L1 could also promote EMT progression in ovarian cancer cells." (PMID 37420173, 2023).
endometrial cancer (5 papers, 2018 to 2023). Primary or metastatic malignant neoplasm involving the endometrium (mucous membrane that lines the endometrial cavity). "In recent years, the expression of EFEMP2 in different types of cancers has been controversial, in that, in cancers, such as breast, lung, and endometrial cancers, EFEMP2 plays a protective role." (PMID 37420173, 2023).
glioblastoma (5 papers, 2020 to 2023). The most malignant astrocytic tumor (WHO grade IV). "In both the CGGA (all grades, n = 297) and TCGA (glioblastoma, n = 418) array datasets, patients with strong EFEMP2 expression were primarily harboring wild type IDH1, whereas most of the ones with low EFEMP2 expression harbored IDH1 mutation." (PMID 32396873, 2020). "Further validation by RT-qPCR revealed SMIM30, SNORA53 and LINC01354 were significantly upregulated and EFEMP2 markedly downregulated in 15 glioblastoma samples compared to 6 controls samples." (PMID 32962742, 2020). "In TCGA (glioblastoma, n = 520), patients with high expressions of EFEMP2 were concentrated in Classical and Mesenchymal subtypes, whereas patients with weak EFEMP2 expressions primarily presented as G-CIMP and Proneural subtypes, which are usually associated with optimistic outcomes." (PMID 32396873, 2020).
bladder cancer (3 papers, 2019 to 2022). "EFEMP2 has been found related to survival rate; downregulation of EFEMP2 leads to a higher death rate in bladder cancer." (PMID 35782114, 2022). "The current study focused on exploring the role of EFEMP2 in bladder cancer (BCa)." (PMID 31592144, 2019). "However, whether there is also a difference in EFEMP2 expression in bladder cancer and whether it plays a biological role in bladder cancer remains to be uncovered." (PMID 31592144, 2019). "Volcano plot was performed to represent the significantly different RNAs between bladder cancer specimens and adjacent non-cancer specimens, Heatmap was used to show the unsupervised clustering of top 50 down-regulated RNAs, and EFEMP2 is one of the members." (PMID 31592144, 2019).
lung carcinoma (3 papers, 2016 to 2023). "EFEMP2 exhibits oncogenic activity such as promoting proliferation of lung cancer cells." (PMID 32396873, 2020). "EFEMP2 and EHD2 have been reported to inhibit the invasion and metastasis of lung cancer cells by regulating the epithelial-mesenchymal transition (EMT) process and MMP activity." (PMID 37291533, 2023).
lymph node metastasis (3 papers, 2015 to 2023). "High expression of EFEMP2 in CC is associated with lymph node metastasis and poor prognosis, and may promote angiogenesis." (PMID 37449209, 2023).
colon cancer (2 papers, 2013 to 2015). "Interestingly, genes that are associated with colon cancer progression (ANTXR1, EFEMP2, SULF1, TAGLN, VCAN, ZEB1 and ZEB2) were upregulated in patients co-overexpressing TAZ-AXL-CTGF." (PMID 23372686, 2013). "Colon cancer biomarkers were also differentially expressed in these two groups of patients, namely EFEMP2, a serum biomarker for early detection of colon cancer and SULF1, a protein important in colon cancer diagnosis and whose serum level is elevated in patients with colon adenomas." (PMID 23372686, 2013).
colorectal cancer (2 papers, 2013 to 2020). A primary or metastatic malignant neoplasm that affects the colon or rectum. "EFEMP2 has been proposed as a potential serum biomarker for the early detection of colorectal cancer." (PMID 32396873, 2020).
Aortic root aneurysm (1 paper, 2023). An abnormal localized widening (dilatation) of the aortic root. "Two of the authors published an autosomal recessive mutation of the EFEMP2 gene in nine children from four Saudi families with familial aortic root aneurysms." (PMID 38249165, 2023). "Family screening showed multiple siblings with aortic root aneurysms and an abnormality in the EFEMP2 gene." (PMID 38249165, 2023).
arachnodactyly (1 paper, 2019). "Mutations in fibulin-4 (EFEMP2) cause ARCL1B, characterised by severe cardiovascular abnormalities, joint laxity and arachnodactyly." (PMID 30016650, 2019).
Ascites (1 paper, 2023). Accumulation of fluid in the peritoneal cavity (between the layers of the peritoneum that lines the abdomen). "ES-2 NC, EFEMP2 shRNA infected cells and EFEMP2 shRNA and PD-L1 cDNA co-transfected cells were injected intraperitoneally in nude mice, with 1.5 × 107 cells for each mouse to establish an ascites tumor model." (PMID 37420173, 2023).
diabetes mellitus (1 paper, 2024). A metabolic disorder characterized by abnormally high blood sugar levels due to diminished production of insulin or insulin resistance/desensitization. "The high expression groups of PENK, EFEMP2, UBAP1, MAFF and KLF4 were mainly concentrated on diabetes mellitus (DM)." (PMID 38332532, 2024).
glaucoma (1 paper, 2012). Increased pressure in the eyeball due to obstruction of the outflow of aqueous humor. "While mutation of EFEMP2 does not appear to be a direct cause of general Anterior Segment Dysgenesis (ASD; unpublished data), it remains an interesting candidate gene for glaucoma and other anterior segment diseases." (PMID 22919265, 2012).
mastitis (1 paper, 2023). Inflammation of breast tissue during lactation or postpartum due to an obstructed duct or infection. "The role that EFEMP2 could play in the development of mastitis is less clear." (PMID 37685039, 2023).
tumor (23 papers, 2015 to 2025). "Epidermal growth factor-containing fibulin-like extracellular matrix protein 2 (EFEMP2), an extracellular matrix protein, is highly associated with tumor invasion and metastasis." (PMID 31592144, 2019). "In the current study, we first depicted that the expression of EFEMP2 was significantly associated with tumor stage and grade in human BCa, and low EFEMP2 expression was an independent predictive factor of the relapse, progression and metastasis." (PMID 31592144, 2019). "The tumorigenicity of cancer cells transfected with EFEMP2 shRNA was worse, the tumor growth rate was slower, and the average tumor volume was smaller, moreover, tumor abdominal dissemination was suppressed." (PMID 37420173, 2023). "On the contrary, the tumor growth rate was significantly accelerated in the EFEMP2 overexpression group, and the tumor volume was greater than that in the control group." (PMID 37420173, 2023). "We further identified the downstream signaling pathway of EFEMP2 and its possible effector proteins using the tumor signaling pathway chip." (PMID 37420173, 2023). "Next, we evaluated EFEMP2 expression in human lungs surgically resected for tumor removal at the Shimane University Hospital." (PMID 37400563, 2023). "The EFEMP2 overexpression group had a slower growth of neoplasms compared with those empty vector group, and the average weight of tumors was light than the empty vector group." (PMID 31592144, 2019). "Collectively, our observations revealed that EFEMP2 is a blocker of tumor progression and metastasis in BCa." (PMID 31592144, 2019). "The 22 common hub genes, except DDX3Y, SEP15, and EFEMP2, from both groups were also common in the hub of hub genes, with the mean degree of the common hub of hub genes being 4.8 (range, 2–10) in the normal and 4.27 (range, 2–12) in the tumor." (PMID 40457491, 2025). "As a fibulin family member with EGF-like calcium-binding domains, EFEMP2 is essential for cellular architecture and signalling within tumours and may influence glycosaminoglycan metabolism." (PMID 39063109, 2024). "In vivo experiments in nude mice also demonstrated that PD-L1 overexpression could reverse the inhibitory effect of EFEMP2 down-expression on subcutaneous tumor growth and abdominal spread." (PMID 37420173, 2023). "Given the relationship between the STEAP family of proteins and tumor progression, we wanted to clarify whether these changes in EFEMP2 affect other STEAP proteins." (PMID 36316642, 2022). "An investigation observed an enriched level of tumor cell growth and overall survival–related EFEMP2 expression in macrophage M0, which could potentially support our findings." (PMID 34899849, 2021). "To further evaluate the influence of EFEMP2 on tumor immunology, we performed Pearson correlation analysis and found that EFEMP2 exhibited significant correlations with most of the critical immunology actions, especially interferon related response and natural killer cell mediated cytotoxicity." (PMID 32396873, 2020). "However, little relationship was found between EFEMP2 expression and other clinical features such as patient's gender (p=0.578), age (p=0.594), tumor size (p=0.259), multiplicity of tumor (p=0.838) and smoking history (p=0.876)." (PMID 31592144, 2019). "Meanwhile, EFEMP2 also play a certain role in tumor invasion and metastasis." (PMID 31592144, 2019). "Moreover, tumor grade (HR:2.285; 95% CI, 1.552-3.363; p<0.001) and low EFEMP2 expression (HR:1.825; 95% CI, 1.169-2.849; p=0.008) were the prognostic factors for DFS." (PMID 31592144, 2019). "However, influenced by the tumor microenvironment, EFEMP2 played different roles in different tumors." (PMID 31592144, 2019).
tumor (continued). "By real-time qPCR, we further examined the expression of selected genes (Pkm, Ppp1r13l, Vamp3, Ctnnb1, Tbc1d4, Ppp1r21, C1qtnf9, Fgf3 and Efemp2) that are known to be involved in the tumor development or potentially relevant for establishment of malignant transformation." (PMID 29073177, 2017). "In addition, because the STEAP family is known to play a critical role in the tumor progression of various cancers, we went on to evaluate whether changes in EFEMP2 affected the expression of the STEAP proteins." (PMID 36316642, 2022). "We found that the expression levels of EFEMP2, EHD2, FSTL3 and ALOX5 were decreased in tumor tissues, whereas COL3A1 was significantly increased in tumor samples." (PMID 37291533, 2023). "Seven hub genes (AXL, EFEMP2, VIM, EHD2, FSTL3, ALOX5, HSPB8) were downregulated in tumor samples, while COL3A1 was upregulated in tumor samples in the TCGA dataset." (PMID 37291533, 2023). "And we found a negative correlation between EFEMP2 expression and high tumor stage, high tumor grade, patients with low EFEMP2 expression had a much poorer survival than those patients with high EFEMP2 expression." (PMID 31592144, 2019). "Interestingly, our proteomic analysis has uncovered three proteins that were present either in tumor ECM alone (COL10A1) or in tumor and adjacent mucosa (EFEMP2 and vWF) and were absent in most distant mucosa samples." (PMID 35340765, 2022).
cancer (12 papers, 2015 to 2025). A tumor composed of atypical neoplastic, often pleomorphic cells that invade other tissues. "Among these, EFEMP2, identified from the UPGs (upregulated prognostic genes) pool, stands out due to its significant function in molecular cancer mechanisms." (PMID 39063109, 2024). "Fibulin-like extracellular matrix protein 2 (EFEMP2) has been reported to be related to the progression of various cancers." (PMID 37420173, 2023). "In the current research, we found that the expression of EFEMP2 in normal bladder tissues and cells were significantly higher than those in cancer tissues and cells." (PMID 31592144, 2019). "EFEMP2 has been reported to have implications in the advancement of different cancer types." (PMID 39342078, 2024). "Cancer cells that overexpressed EFEMP2 were more prone to tumorigenesis." (PMID 37420173, 2023). "The growth support of αSMA positive cells towards cancer cells might be diverse, suppression of bone formation, on one hand, direct secretion of growth factors (Efemp2) on the other hand." (PMID 29988965, 2018). "Recently, it has been reported that EFEMP2 may also participate in carcinogenesis by regulating EMT and this could be a mechanism EFEMP2-mediated cancer invasion and metastasis." (PMID 31592144, 2019).